TMPRSS13 (transmembrane serine protease 13)
Description:
Serine protease. Cleaves the proform of PRSS8/prostasin to form the active protein. Cleaves the proform of HGF to form the active protein which promotes MAPK signaling. Promotes the formation of the stratum corneum and subsequently the epidermal barrier in embryos (By similarity).
Synonyms: MSP; TMPRSS11; MSPL; MSPS
Tractability: Antibody: UniProt places it where antibodies can reach, with high confidence; UniProt predicts a signal peptide or a membrane-spanning region; its Gene Ontology location is reachable by antibodies, with medium confidence; the Human Protein Atlas places it where antibodies can reach. PROTAC: ubiquitination databases record sites on it.
Gene: Protein-coding gene on chromosome 11 (117,900,641 to 117,929,459, reverse strand). Ensembl gene ENSG00000137747.
Subcellular location: Cell membrane; Secreted; Cytoplasm
Subcellular location (Human Protein Atlas): Nucleoplasm; Plasma membrane; Predicted to be secreted
Gene Ontology:
Molecular function: serine-type endopeptidase activity; serine-type peptidase activity
Biological process: protein processing; proteolysis
Cellular component: blood microparticle; cytoplasm; extracellular region; plasma membrane; membrane
Genetic constraint (gnomAD): Loss-of-function variants: 49 observed, 64.28 expected, observed/expected ratio (o/e) 0.76, 90% interval 0.61 to 0.97. The upper end of that interval is the gene's LOEUF score, 0.97, which puts it in group 4 of 6, group 1 being the genes least tolerant of losing a copy. Missense variants: 612 observed, 731.38 expected, observed/expected ratio (o/e) 0.84, 90% interval 0.78 to 0.89. Synonymous variants: 266 observed, 284.57 expected, observed/expected ratio (o/e) 0.93, 90% interval 0.85 to 1.03.
Homologues: Orthologues: macaque TMPRSS13 (96% identical), chimpanzee TMPRSS13 (93% identical), mouse Tmprss13 (82% identical), rat Tmprss13 (81% identical), pig TMPRSS13 (78% identical), dog TMPRSS13 (78% identical), guinea pig TMPRSS13 (75% identical), tropical clawed frog tmprss13 (33% identical), zebrafish tmprss13b (32% identical), Drosophila melanogaster Sb (21% identical), Drosophila melanogaster CG17242 (9% identical). Paralogues in human: ST14 (28% identical), TMPRSS7 (27% identical), TMPRSS6 (27% identical), TMPRSS3 (25% identical), TMPRSS15 (25% identical), TMPRSS2 (25% identical), TMPRSS5 (23% identical), HPN (22% identical), TMPRSS11E (22% identical), TMPRSS9 (20% identical), TMPRSS11A (20% identical), TMPRSS11D (20% identical), and 5 more.
Diseases named in the same sentence as TMPRSS13 in open-access papers:
TMPRSS13 is named in the same sentence as 18 diseases in open-access papers, as found by Europe PMC text mining. Sharing a sentence is not in itself a finding about the gene and the disease. The quoted sentences say what the papers report.
breast carcinoma (5 papers, 2016 to 2025). "At the molecular level, knockdown of TMPRSS13 in breast cancer cells led to increased protein levels of the tumor-suppressive protease prostasin, which was identified as a potential novel target for TMPRSS13." (PMID 35163586, 2022). "We have previously shown that endogenous TMPRSS13 levels affect endogenous prostasin protein levels in breast cancer cells and that recombinant TMPRSS13 cleaves and activates the pro-form of prostasin in HEK293T cells." (PMID 34562451, 2021). "Additional recurrently mutated genes detected in the 16 PALB2-associated breast cancers profiled by WES included CTNNA2, TMPRSS13, KRTAP4–11, LAMA5, KALRN, and COLL22A1 (all, n = 3)." (PMID 31428676, 2019). "These compounds could serve as molecular tools to confirm the involvement of TMPRSS13 proteolytic activity in various pathologies, including colorectal and breast cancers." (PMID 39976239, 2025). "Regulation of prostasin levels may be a mechanism that contributes to the pro-oncogenic properties of TMPRSS13 in breast cancer." (PMID 35163586, 2022).
colorectal cancer (4 papers, 2020 to 2022). A primary or metastatic malignant neoplasm that affects the colon or rectum. "Mutations in TMPRSS13 have been previously identified in colorectal adenomas, and their regional presentation in our study (lesion-common mutations) indicates that TMPRSS13 mutations in colorectal cancers can be early events like APC or KRAS mutations." (PMID 32023847, 2020). "In the present study, we found TMPRSS13 to be differentially expressed at both the transcript and protein levels in human colorectal cancer (CRC)." (PMID 32807808, 2020). "Transmembrane Protease, Serine 13 (TMPRSS13, also known as Mosaic Serine Protease Large-Form (MSPL)), a TTSP that belongs to the hepsin/TMPRSS subfamily, has recently been implicated as a pro-oncogenic protease in both breast and colorectal cancers." (PMID 34562451, 2021). "The hepsin/TMPRSS subfamily is a subclassification of the TTSP family and includes transmembrane protease serine 13 (TMPRSS13), a protein whose ability to promote breast and colorectal cancer (CRC) progression in vivo due to its antiapoptotic properties has been recently reported." (PMID 36085166, 2022).
viral infections (4 papers, 2020 to 2025). "Increasing the selectivity for TMPRSS13 would not only reduce the risk of side effects in therapeutic applications but also provide a valuable research tool, enabling more precise investigations on TMPRSS13 function in viral infections and cancer biology." (PMID 39976239, 2025). "Here, using a combination of biochemical and immunological methods, we show that IL4I1 indeed binds to the transmembrane protein TMPRSS13, a serine protease recently shown expressed and important in human cancers and in viral infections." (PMID 36131918, 2022). "Therefore, TMPRSS13 has emerged as a novel target for the design and discovery of drugs for treating cancer and viral infections." (PMID 34562451, 2021). "Therefore, TMPRSS13 with its accessibility on the cell surface represents a candidate target for the development of inhibitors for treating cancer and viral infections." (PMID 34562451, 2021).
adenoma (3 papers, 2018 to 2025). A neoplasm arising from the epithelium. "Lin and colleagues characterized the mutational alterations using WES and proposed four genes (CTNNB1, KRTAP4-5, GOLGA8B, and TMPRSS13) as the potential somatic drivers in conventional adenomas." (PMID 40757636, 2025). "APC is the gene most frequently mutated in conventional colon adenomas; four genes recurrently mutated in adenomas CTNNB1 (catenin-β1), KRTAP4-5 (keratin-associated protein 4–5), GOLGA8B (golgin A8 family member B) and TMPRSS13 (transmembrane protease, serine 13) had the oncogene pattern." (PMID 29652830, 2018).
influenza (3 papers, 2012 to 2020). An acute viral infection of the respiratory tract, occurring in isolated cases, in epidemics, or in pandemics; it is caused by serologically different strains of viruses (influenzaviruses) designated A, B, and C, has a 3-day incubation period, and usually lasts for 3 to 10 days. "TMPRSS13 is also expressed in mouse and human respiratory epithelium and several studies show a role for TMPRSS13 in influenza infection by proteolytically modifying the viral protein hemagglutinin, which is necessary for virus infectivity." (PMID 32807808, 2020). "Other candidate TTSPs worth testing in SARS-CoV entry assays are MSPL and TMPRSS13, as they have been found to cleave certain influenza HAs." (PMID 22590686, 2012).
colon adenocarcinoma (1 paper, 2020). "Strong expression of TMPRSS13 was detected in epithelial-derived colon adenocarcinoma." (PMID 32807808, 2020).
colorectal adenocarcinoma (1 paper, 2020). The most common type of colorectal carcinoma. "The DLD-1 (high TMPRSS13 expression) and HCT116 (low TMPRSS13 expression) cell lines are both derived from colorectal adenocarcinomas." (PMID 32807808, 2020). "Evaluation of differential expression of TMPRSS13 in CRC was conducted using normal and cancerous tissue samples with grades ranging from I to III (Normal colon, N = 14; colorectal adenocarcinomas Grade I, N = 16; Grade II, N = 65; and Grade III, N = 23)." (PMID 32807808, 2020).
colorectal tumor (1 paper, 2020). "Together, these findings demonstrate differential TMPRSS13 protein expression in CRC, validating increased levels of transcripts as being accompanied by increased protein levels, and indicating a proteolytic imbalance in the colorectal tumor microenvironment." (PMID 32807808, 2020).
lung carcinoma (1 paper, 2021). "The active form of TMPRSS13 is expressed in human lung as well as nasal tissue, and siRNA-mediated knockdown of TMPRSS13 in Calu-3 human lung cancer cells resulted in a significant reduction in SARS-CoV-2 replication." (PMID 34562451, 2021).
cancer (7 papers, 2019 to 2025). A tumor composed of atypical neoplastic, often pleomorphic cells that invade other tissues. "Crosstalk between TMPRSS13 and Bcl-2 associated pathways may contribute to the increased apoptotic effect we observed; the implications of such a connection are significant, as Bcl-2 is often upregulated in cancer, including CRC55." (PMID 32807808, 2020). "In cancers, for example, TTSPs, such as matriptase, matriptase-2, hepsin, and TMPRSS13, promote cancer progress by degrading extracellular matrix proteins and activating signaling pathways." (PMID 37509434, 2023). "In cancer, TMPRSS13 plays a promotional role by supporting primary tumor growth and metastasis in vivo." (PMID 34562451, 2021). "We have previously shown that this antibody can detect endogenous TMPRSS13 in cancer cells, using siRNA-mediated TMPRSS13 silencing to confirm specificity." (PMID 34562451, 2021). "Recently, it has been shown that TMPRSS13 has antiapoptotic properties and that the protease promotes cancer progression in vivo." (PMID 34562451, 2021). "In parallel experiments, PNGase F was used to remove N-linked glycans from endogenous TMPRSS13 in whole cell lysates from DLD-1 and BT-20 cancer cells." (PMID 34562451, 2021). "We detected glycosylated forms of endogenous TMPRSS13 in human cancer cells using tunicamycin-mediated inhibition of the N-glycosylation process and PNGase F-mediated removal of N-glycans." (PMID 34562451, 2021). "After seeking to identify uncharacterized TTSPs dysregulated in cancers, we discovered that the TMPRSS13 transcript is upregulated in CRC." (PMID 32807808, 2020). "In summary, this study represents a comprehensive characterization of TMPRSS13 in CRC, highlighting cancer-associated dysregulation of this TTSP and underscoring it as a critical component of CRC cell survival and protection from drug-induced apoptosis." (PMID 32807808, 2020). "Immunohistochemical analyses revealed consistent high expression of TMPRSS13 protein on the cancer cell surface in CRC patient samples; in contrast, the majority of normal colon samples displayed no detectable expression." (PMID 32807808, 2020). "Immunohistochemistry indicated increased TMPRSS13 protein levels in both well-differentiated and poorly differentiated cancers, suggesting that this protease is a potential promoter of CRC progression." (PMID 32807808, 2020). "Inhibition of TMPRSS13 proteolytic activity could also be valuable for investigating its role in cancer and developing therapeutics." (PMID 39976239, 2025). "DC-SIGN interacts with Serine-II Protease MSPL/TMPRSS13 on glycan-free cancer cells." (PMID 38137417, 2023). "Furthermore, TMPRSS13 promotes cell survival, invasion, and resistance to drug-induced apoptosis in cancer cells." (PMID 34562451, 2021). "Importantly, our observations from exogenously expressed TMPRSS13 in HEK293T cells extend to endogenous forms of TMPRSS13 in cancer cell lines." (PMID 34562451, 2021). "TMPRSS13, a member of the Type II Transmembrane Serine Proteases (TTSP) family, is involved in cancer progression and in respiratory virus cell entry." (PMID 39976239, 2025). "Upon treatment of live cancer cells with tunicamycin for 48 h, whole cell lysates were analyzed by reducing SDS-PAGE and western blotting using the α-intra-TMPRSS13 antibody." (PMID 34562451, 2021). "In poorly differentiated carcinomas (grade III), TMPRSS13 expression mainly localized to the cell surface, with some areas displaying dispersed staining and the majority of samples showing low to moderate staining." (PMID 32807808, 2020). "Because the biochemical and cell biological features of TMPRSS13 are still relatively uncharacterized and have not been studied in the context of cancer, the only two candidate mammalian substrates for TMPRSS13 reported to date are pro-HGF and ENaC25,26." (PMID 32807808, 2020). "These properties of TMPRSS13 have not previously been described in any cancer type." (PMID 32807808, 2020).
cancer (continued). "The type II transmembrane serine protease (TTSP) family encompasses several proteases that play critical roles in cancer progression; however, the expression or function of the TTSP TMPRSS13 in carcinogenesis has not been examined." (PMID 32807808, 2020).
tumor (6 papers, 2016 to 2023). "Fisher’s exact test revealed that somatic mutations in CSPG4, DNAH11, INADL and TMPRSS13 were significantly associated with PD-L1-positive expression in RCC tumor cells." (PMID 30349421, 2018). "Silencing TMPRSS13 can significantly suppress breast cancer progression both in vitro and in vivo by decreasing proliferation, enhancing apoptosis and inhibiting invasion, resulting in the inhibition of overall tumour burden and deficiency of detectable tumour growth." (PMID 36993976, 2023). "PRSS8 (a serine protease) accumulation mediated by TMPRSS13 knockdown is a potential tumour-suppressive mechanism." (PMID 36993976, 2023). "In this context, one study has shown that genetic ablation of Tmprss13 can enhance apoptosis in tumor cells in mice." (PMID 36085166, 2022). "Moreover, our study revealed that 4 somatically mutated genes, including CSPG4, DNAH11, INADL and TMPRSS13, might act as promising predictive factors of PD-L1-positive expression in RCC tumor cells." (PMID 30349421, 2018). "Moreover, 4 somatically mutated genes, including CSPG4, DNAH11, INADL and TMPRSS13, might be promising predictive factors of PD-L1-positive expression in RCC tumor cells." (PMID 30349421, 2018). "Among the 26 RCC cases, the PD-L1-positive rate in tumor cells was higher in samples with the 4 somatically mutated genes, including CSPG4, DNAH11, INADL and TMPRSS13, than in samples without those (P > 0.05)." (PMID 30349421, 2018). "In this study, among the 26 RCC cases, PD-L1-positive rate in tumor cells was significantly higher in specimens with 4 somatically mutated genes, including CSPG4, DNAH11, INADL and TMPRSS13, than in samples without those (P < 0.05)." (PMID 30349421, 2018).
infection (5 papers, 2017 to 2025). The state of being infected such as from the introduction of a foreign agent such as serum, vaccine, antigenic substance or organism. "The transmembrane protease, serine 13 gene (TMPRSS13, 11q23), a splice variant of mosaic serine protease large form (MSPL), encodes a family of the type II transmembrane serine proteases which plays critical roles in maintaining homeostasis, infection, and tumorigenesis." (PMID 28249600, 2017). "The presence of TMPRSS13 facilitated the entry of GFP+ LVS into HEK-T cells relative to HEK cells, resulting in 40 ± 8.9% and 3.7 ± 2.1% GFP+ cells at 48 hours post-infection, respectively." (PMID 36131918, 2022).
TMPRSS13 also shares sentences with these, for which no sentence is quoted: colon adenoma (1 paper); colorectal adenoma (1); COVID-19 (1); lung adenocarcinoma (1); malaria (1); pulmonary disease (1).